AKT3 (AKT serine/threonine kinase 3)
Diseases named in the same sentence as AKT3 in open-access papers (continued):
Sharing a sentence is not in itself a finding about the gene and the disease.
tumor (continued). "MiR-1258 serves as a tumor suppressor by targeting AKT3, which leads to reduced cell proliferation and enhanced cell cycle arrest at the G0/G1 phase, thus halting tumor progression." (PMID 39419925, 2025). "Increasing evidence highlights the distinct roles of AKT1, AKT2, and AKT3 in tumor progression and radiation resistance." (PMID 40725100, 2025). "PDXCs from MAS98.12PR and MAS98.12 generally preserved the main molecular differences detected in the PDXs i.e. up-regulation of SFKs, MAPK/ERK pT202/204 and AKT3 in the resistant tumor tissue." (PMID 39390250, 2024). "It is suggested that CAFs in HNSCC (including OSCC) are mainly comprised of myofibroblasts, playing a central role in tumor progression through Akt3 expression." (PMID 38279300, 2024). "The oncogenic circWHSC1, which is highly expressed in BC tissues and cells, regulates TNBC cell growth, migration, invasion, and survival by sponging the tumor suppressor miR-212-5p, thus promoting AKT3 expression." (PMID 37998329, 2023). "miR-15a and -16 exert tumor-suppressive activity by targeting AKT serine/threonine protein kinase (AKT3) and are downregulated in MM tumor cells." (PMID 37048103, 2023). "The downregulation of AKT3 can be achieved by increasing tumor suppressor miRNAs or by suppressing oncogenic miRNAs." (PMID 37998329, 2023). "Their tumor suppressor roles have been demonstrated to involve the direct inhibition of AKT3 in PTC cells." (PMID 37998329, 2023). "AKT3 activates several genes associated with the EMT in CRC cells and promotes tumor invasion and metastasis." (PMID 36927770, 2023). "RNA transcriptomic analysis showed a gene significantly associated with the low cytoplasmic S100A2 group (AKT3, TAGLN, MYLK, FGD6 and ETFDH), which correlated with tumour development and progression." (PMID 37476187, 2023). "AKT3 expression is regulated by the tumor inhibitor miR-582-5p, whose expression is significantly diminished in human EC tissues." (PMID 37998329, 2023). "Members of the AKT family include three isoforms, AKT1, AKT2, and AKT3, which are involved in different mechanisms of tumor progression." (PMID 36927770, 2023). "Further studies have validated that several tumor suppressor miRNAs that directly suppress AKT3 expression are lost or downregulated in HCC cells." (PMID 37998329, 2023). "More recently, a circular AKT3 transcript has been shown to exert tumor suppressive function in glioblastoma cells, presumably by inhibiting the PI-3 kinase signaling." (PMID 35892586, 2022). "We found that TGFA, SHC1, PIK3CD, GAB1, and AKT3 were negatively correlated with six tumor immune cells in KIRC, and EIF4EBP1 was positively correlated with macrophage infiltration." (PMID 35903358, 2022). "In the case of HCC, miR-582-3p has been demonstrated to be downregulated, and its overexpression reduces cell proliferation and induces cell cycle arrest in the G0/G1 phase by targeting CDK1 and AKT3, suggesting it to be a tumor suppressor." (PMID 35609318, 2022). "AKT3 was, indeed, a major determinant of tumor architecture, since its expression (copies/μL) was inversely related to the SET percentage (Spearman’s rho = −0.36; p = 0.0002)." (PMID 35053468, 2022). "The PI3K/Akt pathway can be activated in tumor cells through mutations or amplification of PIK3CA, loss of PTEN function and/or overexpression of Akt1, Akt2 and Akt3." (PMID 36291790, 2022). "AKT isotypes, such as AKT1, AKT2 and AKT3, have been suggested as therapeutic targets for angiogenesis-related abnormalities such as tumor or ischemic injury." (PMID 36286049, 2022). "It has been reported that the miR-203 up regulation and AKT3 down regulation reduced tumor cell migration, increase E-cadherin, and reduce vimentin expression levels in PTC cells." (PMID 35659780, 2022). "The miR-338-3p also significantly suppressed the cell migration of TC cells and repressed tumor development in vivo by targeting AKT3." (PMID 35659780, 2022).
tumor (continued). "Some well known oncogenes, such as AKT3, and tumor suppressors, such as RB1 and PARK2 emerged in the high or low CNV regions." (PMID 35244719, 2022). "The interaction of AKT1, AKT3, and DNA-PKcs promote tumor-cell proliferation and survival after irradiation." (PMID 34665844, 2021). "In DEC-induced DNA reprogramming, chimeric antigen receptor T (CAR T) cells, compared to the control group, differentially expressed genes including AKT3, and it is expected that this can enhance antitumor effects or reduce tumor recurrence." (PMID 34944006, 2021). "In contrast, knockdown of AKT3 leads to an impaired spheroid growth and tumor growth in vivo via an upregulation of p27." (PMID 33670586, 2021). "It is worth mentioning that mining the data from the TargetScan database, the tumor suppressor miR-637 has other Akt isoforms as gene targets like Akt2 and Akt3 in addition to Akt1." (PMID 33911067, 2021). "AKT3 expression in CAFs was significantly positively correlated with the proportion of α-SMA-positive CAFs (p < 0.001), number of CD68+ tumor-associated macrophages (p = 0.01), number of CD1a+ dendritic cells (p = 0.02), and number of CD3+ T cells (p = 0.03)." (PMID 33799788, 2021). "For instance, AKT3 can be regulated by miR-582-5p to promote tumor cell proliferation in gastric cancer." (PMID 34882061, 2021). "AKT is a serine/threonine protein kinase, also known as protein kinase B. The AKT family mainly includes Akt1, Akt2, and Akt3, among which Akt1 plays a significant role in promoting tumor cell proliferation and inhibiting tumor cell metastasis." (PMID 34484402, 2021). "Tumours derived from clone OE19 showed elevated AKT3, PGC1a and VDAC1 confirming the effect of PPARG on this pathway." (PMID 33654198, 2021). "The effect of PPARG driven AKT3 up-regulation results in an accumulation of PGC1α, which drives mitochondrial biogenesis and tumour growth and development." (PMID 33654198, 2021). "In clinical samples from 72 HNSCC patients, AKT3 protein expression in CAFs correlated positively with myofibroblastic CAF infiltration into the tumor microenvironment." (PMID 33799788, 2021). "miR-29b prevented tumor angiogenesis by targeting AKT3 and inhibited Akt3-mediated VEGF and C-myc activations." (PMID 34956857, 2021). "Based on our collected kidney normal and RCC samples, we compared the expression of AKT1 (AKT), AKT2 and AKT3 in RCC tumor tissues versus normal tissues." (PMID 34384473, 2021). "MALAT1 can also competitively bind to miR-181a-5p, which prevents miR-181a-5p from binding to AKT3 mRNA, thereby up-regulating the level of AKT3 protein and ultimately promoting tumor growth in GC." (PMID 34356052, 2021). "As substantial Akt1, Akt2 and Akt3 mRNA levels were detected in the majority of tumor samples of HNSCC patients, we can conclude that the target of MK2206 is present in HNSCC patients." (PMID 34568028, 2021). "We then divided the available RCC tumor samples into low versus high expression of AKT1, AKT2 and AKT3 and performed a patient survival association analysis." (PMID 34384473, 2021). "In the case of AKT3, the expression of AKT3 in RCC tumor showed a huge variation in the individual RCC tumor samples." (PMID 34384473, 2021). "Multiple studies have demonstrated that AKT3 is involved in almost all processes during tumor initiation and progression, including proliferation, migration, invasion, and drug resistance." (PMID 34882061, 2021). "This further supports the AKT3 key role in sevoflurane induced tumor growth, invasion and tumor recurrence." (PMID 34199634, 2021). "In interstitial colorectal cancer, AKT3 played a promotive role in tumor cell growth and was potentially correlated to the malignant epithelial-mesenchymal transition (EMT)." (PMID 34882061, 2021). "Of the 16 kinases originally identified in the tumour dataset, 6 were also found to be differentially expressed in the cell line panel: AKT3, MYLK, PRKD1, AXL, NUAK1 and DCLK1." (PMID 33673003, 2021).
tumor (continued). "miR-29 is considered a tumor suppressor miRNA given its ability to repress genes involved in proliferation and cell survival, such as AKT3, DNMT3A/B, MCL1, and CDK6, and its frequent downregulation in cancer, including leukemia, ovarian, or breast." (PMID 33808771, 2021). "We have shown that in situ RNA hybridisation for AKT3 on FFPE tumour tissue can be used to identify tumours in which AKT3 is highly expressed in the cancer cell compartment." (PMID 33673003, 2021). "AKT3 promotes apoptosis of different types of tumor cells such as gastric cancer, endometrial carcinoma and breast cancer." (PMID 34103010, 2021). "We also found that DSCAM-AS1 and AKT3 expression was downregulated, while miR-384 was upregulated in xenograft tumor of sh-DSCAM-AS1/LOVO group when compared to sh-NC/LOVO group." (PMID 32453706, 2020). "By the way, although AKT isoforms are observed to play different roles in GBM, including AKT3 delays tumor progression, as a matter of fact, the AKT inhibitor perifosine is tolerable but ineffective as monotherapy for GBM." (PMID 32333246, 2020). "In addition, emerging evidence indicated the potential therapeutic value of tumor-related functional peptides encoded by circRNAs, especially cancer-inhibiting peptides/proteins, such as β-catenin-370aa encoded by circβ-catenin, circPPP1R12A-73aa by circPPP1R12A, and AKT3-174aa by circ-AKT3." (PMID 33069241, 2020). "Marked overexpression of DUSP4, CD44, MUM1/IRF4, BCL-2, CD146/MUC18, IGF1R, and AKT3 was observed in the tumour cells in all mUM, compared to the background hepatocytes." (PMID 33008022, 2020). "Yet, its role in tumor progression is controversial as some studies have showed an inhibitory effect of AKT3 on cell migration and invasion." (PMID 31357505, 2019). "By analyzing the most differentially expressed circRNAs between tumor group and normal group, we identified circ-AKT3." (PMID 31470874, 2019). "Due to the significant lower level of hsa_circ_0017250 (termed as circ-AKT3) in tumor group compare with that in normal group (11 folds), we next explored its endogenous expression." (PMID 31470874, 2019). "Tumor‐bearing nude mice assay results showed that LOC101928316 overexpression can significantly inhibit the p‐AKT3 and p‐mTOR protein expression levels in bearing nude tumor tissues." (PMID 31207155, 2019). "Subsequently, we use an immunohistochemical assay to determine the protein expression of p‐AKT3 and p‐mTOR from nude mice tumor tissues." (PMID 31207155, 2019). "The p‐AKT3 and p‐mTOR proteins expression levels in isolated tumor tissues also were analyzed by immunohistochemical." (PMID 31207155, 2019). "PTMScan experiment found the upregulated Rictor in NFPAs and increased phosphorylations at residues Ser472 in Akt3, which suggested that activation of mTORC2 contributed to the tumor progression in NFPAs." (PMID 31920959, 2019). "AKT1 knockdown has an anti-tumor effect, whereas AKT2 ablation can promote tumor growth and AKT3 ablation has little effect." (PMID 31454965, 2019). "The expression of AKT3 mRNA levels was higher in GC tissues compared with their respective non‐tumour tissue." (PMID 31515938, 2019). "The tumor-suppressor miR-433 directly targets AKT3 and hence attenuates proliferation, cell viability and survival; the latter probably through downregulation of Bcl-2 and upregulation of BAX." (PMID 31752925, 2019). "miR-15b, a bona fide tumor-suppressor miRNA, regulates a number of genes associated with CRC metastases such as AKT3, PIK3R18, GPC633, LIMS134, and TCF4." (PMID 31676795, 2019). "Conversely, in HCC with PTEN null expression, it would determine an even stronger AKT/mTOR pathway activation through AKT3 upregulation, contributing to tumor cell proliferation and invasion." (PMID 31805631, 2019). "The tumor suppressor miR-122 can inhibit the proliferation of HCC cells by blocking the activation of Akt3, Wnt, and Bcl-ω and is expressed at a low level in HCC tissues." (PMID 31815633, 2019).
tumor (continued). "Partial responses are seen in patients with pre-treatment PTEN tumour loss, with pre-treatment AKT phosphorylation, and with pre-treatment AKT3 and RAC1 activating mutations." (PMID 30237495, 2018). "More recently, it has been reported that hsa-miR-29b suppresses tumor growth through simultaneously inhibiting angiogenesis and tumorigenesis by targeting Akt3." (PMID 29361687, 2018). "We detected significant higher proliferation rate in tumor‐bearing glands in Dt mice, both in 8 week‐old mice and in mice older than 12 weeks, further confirming the contribution of Akt3 to ACC progression." (PMID 29282901, 2018). "In conclusion, these data are consistent with the possibility that miR-195 plays a critical functional role in suppressing tumor progression in human GC in vitro and in vivo, probably exerting its role by modulating its target gene AKT3." (PMID 29228608, 2017). "mRNA patterns of AKT3 suggest essential connections with tumor growth and metastasis, as well as a strong biomarker potential when used with 3 other genes (PTTG1, MND1, CENPF)." (PMID 29321820, 2017). "In contrast to the effect of Akt1- and Akt3-knockdown, Akt2-knockdown significantly stimulated tumor growth." (PMID 29090098, 2017). "Lastly, on chromosome 1, both tumours E8 and E9 have a common amplicon at 1qH3-H4 encompassing Akt3; of note, high expression of AKT3 is a feature of human BLBC2." (PMID 28194015, 2017). "The results also suggested that lenti-UCA1-siRNA stably-transfected BGC-823 cells significantly inhibited p-AKT3 and p-mTOR protein expression in isolated tumor tissues of these animals." (PMID 29212166, 2017). "Next, we expanded our analysis to additional tumours from these mice, focusing on expression changes and potential genomic amplifications of the Yap1, Met and Akt3 genes." (PMID 28194015, 2017). "We also determined tumor tissue protein expression of p-AKT3 and p-mTOR using an immunohistochemical assay of tissues from nude mice." (PMID 29212166, 2017). "Immunohistochemistry was used to analyze the p-AKT3 and p-mTOR protein levels in isolated tumor tissues." (PMID 29212166, 2017). "This tumor was BRCA1 mutated, and had an observed increase in expression in AKT3 and PIK3CA, and a significant decrease in expression of PTEN, demonstrating an active PI3K/AKT pathway." (PMID 28649657, 2017). "Akt3 expression was inhibited in 20 μg/mL PGN-treated tumor cells and in 1.5 mg/kg PGN-treated mouse tumor models." (PMID 27708223, 2016). "Conversely, tumors developed from Akt2 KD ID8 cells had the highest (p<0.05) tumor cell proliferation, while Akt3 KD tumors had intermediate proliferation." (PMID 27533079, 2016). "In our in vivo model, we found an increase in tumor cell proliferation in Akt3 knockdown tumors compared to controls, but again this increase was significantly less than that seen in Akt2 KD tumors." (PMID 27533079, 2016). "Ablation of Akt3, both in tumor cells and in the host often led to results that were intermediate between Akt1 and Akt2 knockdown." (PMID 27533079, 2016). "Akt1 KD had the highest (p<0.05), while Akt2 KD had the lowest (p<0.05) incidence of tumor cell apoptosis, while Akt3 KD tumors had less apoptosis than Akt1 KD tumors, but more than Akt2 KD." (PMID 27533079, 2016). "In our study, Akt3 knockdown in tumor cells resulted in increased tumor size compared to controls, but to a lesser degree than that seen with knockdown of Akt2." (PMID 27533079, 2016). "In summary, we have combined experimental and clinical studies to establish MicroRNA-424/Akt3/E2F3 axis functions as tumor suppressor in HCC growth." (PMID 26315541, 2015).
tumor (continued). "The average volume of PC-3 tumor overexpressing AKT3 was twice the average volume of control PC-3 tumors." (PMID 26318033, 2015). "PRAS40 phosphorylation increased in conjunction with tumor burden in WT, Akt2−/− and Akt3−/− mice, however, at the latest time point post-infection, when tumor burden was substantial, PRAS40 phosphorylation was inhibited." (PMID 24722238, 2014). "Conversely, the accelerated growth rate of lung tumors in Akt2−/− and Akt3−/− mice was due to increased cell proliferation and reduced tumor cell apoptosis." (PMID 24722238, 2014). "This analysis revealed that, at both early and late time points, AJEJJenv infected Akt2−/− mice harbored significantly greater numbers of hyperplastic foci/tumors than WT, Akt1−/− and Akt3−/− mice, suggesting that ablation of Akt2 enhances tumor initiation." (PMID 24722238, 2014). "Phospho-mTOR levels increased in conjunction with increased tumor burden in Akt1−/− and Akt3−/− mice, remained constant in Akt2−/− mice and tapered off in WT mice with late stage tumors." (PMID 24722238, 2014). "Phospho-MDM2, which when phosphorylated by Akt enhances cell survival, was slightly increased in WT mice, but remained relatively unchanged in the Akt knockout mice with the exception of a slight decrease in Akt3−/− mice in advanced neoplasms." (PMID 24722238, 2014). "We found that expression of PIK3R1, PIK3R3, and AKT3 significantly enhanced 6.27-, 9.78-, and 4.53-fold respectively in tumor tissues in comparison with arachnoidal tissue by qRT-PCR." (PMID 23285163, 2012). "Recent preclinical studies have shown that inhibitors of PI3K and AKT3 increased apoptosis and stimulated tumour regression." (PMID 21139585, 2011). "Amongst these are notable tumor related genes AKT3, CDKN1A, ESR1, FOXO1, TSC2, ERBB3, and NRG4." (PMID 40522948, 2025). "Moreover, treatment with either an AKT3 inhibitor or an FGFR2 inhibitor significantly attenuates tumor progression in patient-derived xenograft models." (PMID 40057671, 2025). "Although we did not examine concordance of results in the liquid versus the tissue biopsy cohort for alterations in genes other than PIK3CA, PTEN, AKT1, AKT2, and AKT3, our results support the value of blood-based NGS panel testing in providing a comprehensive tumor mutational landscape." (PMID 40597213, 2025). "In addition, the overexpression of AKT3 also increased the expression of vimentin, indicating that AKT3 promotes tumor cell migration." (PMID 38491196, 2024). "Dual-luciferase assays verified that miR-485-3p may want to directly bind to Akt3 mRNA, inhibiting the Akt/mTOR pathway in tumor cells, thus inhibiting cellular glycolysis, proliferation, and invasion, and acting as a tumor suppressor." (PMID 39119480, 2024). "MiR-610 functions as a tumor suppressor and suppresses AKT3 in several human cancers." (PMID 37998329, 2023). "Further, we observed no change in total AKT phosphorylation across those tumors in which AKT2 was depleted, suggesting AKT1 or AKT3 activity may compensate over time to promote tumor growth." (PMID 37894325, 2023). "In endothelial cells, after treatment with exosomes released from MM cells treated with C6-ceramide, the expression of the tumor suppressor miR-29b is induced, but AKT3 is decreased; consequently, endothelial cell proliferation, migration, and angiogenesis are suppressed." (PMID 37998329, 2023). "Furthermore, our research has shown underexpression of genes associated with tumor formation and cancer cell migration, including AKT Serine/Threonine Kinase 3 (AKT3), Serine/Threonine Kinase (ATM) and Pseudopodium Enriched Atypical Kinase 1 (PEAK1) gene." (PMID 38074096, 2023). "On the other hand, among downregulated lncRNAs, LOC101928316 has been shown to induce higher GC cell proliferation, migration, and invasion in vitro, and greater tumor weight in vivo by promoting in some way the higher expression of AKT3, mTOR, and p-mTOR, and a lower expression of PTEN." (PMID 37047267, 2023).